CD44 (CD44 molecule (IN blood group))
Diseases named in the same sentence as CD44 in open-access papers (continued):
Sharing a sentence is not in itself a finding about the gene and the disease.
colon carcinoma (continued). "For example, Cullin-4B (CUL4B) upregulates the expression of the CSC marker CD44 to maintain colon cancer stemness and drive malignant progression to affect prognosis." (PMID 33680915, 2020). "The outcomes of clinical cases and analysis of the cBioPortal for Cancer Genomics database also demonstrated the significant positive correlation among RUNX2, BRG1, and CD44 expressions in colon cancer tissues." (PMID 33071648, 2020). "We evaluated the association of hnRNPA2B1 with BCL2L1, BCL2, MDM2, cMYC, CD44, CDK6, cJUN, and TXNP in HCT116 colon cancer cells treated with 70 μg/ml of the crude extract." (PMID 33163396, 2020). "LS174T colon carcinoma cell lines make use of the CD44 glycoform also known as hematopoietic cell E−/L-selectin ligand (HCELL) to interact with E- and L-selectin." (PMID 30657059, 2019). "Because CD133 and CD44 have been widely validated as CSC markers in a variety of solid tumors including colon cancer, we examined their expression in human colon cancer cells." (PMID 31139149, 2019). "The results showed that the percentages of CD44+ cells, the expression of stem cell core proteins, and the number of tumor spheres formed were increased when colon cancer cells were treated with hM‐Exo." (PMID 31559140, 2019). "The list of other genes upregulated under dynamic microcirculation conditions included one for glycoprotein CD44, a surface marker for colon cancer stem cells." (PMID 30836980, 2019). "As observed in this study and supported by several previous reports, the stem-like CD44+/CD133+ colon cancer cells are chemo-resistant, a characteristic that is enhanced by IL-6 stimulation and the subsequent FRA1 deacetylation." (PMID 30804456, 2019). "Osteopontin seems to be involved in motility regulation by interaction with CD44 in colon cancer cells, which suggests a role for osteopontin in cancer progression." (PMID 31731625, 2019). "Inorder to substantiate these findings, the cytotoxic effect of 5FU, Silibinin and 5FU+ Silibinin was assessed on human colon carcinoma cell line HCT116 derived CD44+ subpopulation." (PMID 30451890, 2018). "Knock-down of CD44 from colon cancer cells lead to reduced expression of anti-apoptotic molecules like Bcl-2, Bcl-xL and increased level of apoptotic molecules like Bax, caspase-3/8/9." (PMID 29747682, 2018). "These 5-FU resistant colon cancer cells exhibited enhanced tumorigenic phenotypes including CD44+ and side-population cells, increased colony and tumor sphere formation." (PMID 30005681, 2018). "It is of interest to note that in all the studies related to the use of CD133 and CD44 as markers for the identification and isolation of colon cancer stem cells, the expression on these cells of EpCAM was noted." (PMID 29652830, 2018). "In some independent reports, it was shown that COLO205 colon cancer cell lines highly express CD44 stem cell marker." (PMID 29339729, 2018). "Transient knock-down of CD44 in human colon cancer cells resulted in upregulation of AKT, whereas overexpression of variant isoforms of CD44 such as v3-10 or v8-10 caused deactivation of AKT." (PMID 29747682, 2018). "CD44+ colon cancer cells display aggressive proliferation, high colony formation, insensitivity to apoptosis and resistance to chemo- and radiotherapies when compared to CD44 negative cells." (PMID 30279970, 2018). "Correspondingly, the expression levels of stem cell-associated genes, including OCT4, Lin28, Lgr5, KLF, Bmi-1, CD44 and SOX2, increased sharply in colon cancer cells upon treatment with exosomes from BM-MSCs or exosomal miR-142-3p." (PMID 30220706, 2018). "In the CD44-silenced HCT116 colon cancer cells, Bax was increased while Bcl-2 and Bcl-xL were downregulated, leading to cleavages of caspase-3, caspase-9 and PARP." (PMID 30279970, 2018).
colon carcinoma (continued). "HCT116 colon cancer cell line derived CD44+ enriched population was screened in the presence of 5FU, Silibinin and 5FU+ Silibinin combination as compared to untreated cells and CD44v6 siRNA transfected cells for assessing their effect on cell viability." (PMID 30451890, 2018). "A recent study showed that Rho kinase plays a key role in the regulation of CD44 expression at the level of colon cancer stem cells." (PMID 29652830, 2018). "In a murine xenograft model of colon cancer, we found treatment with SLV peptide significantly decreased tumor growth and relative abundance of CD133+CD44+ cells; associated with increased phosphorylation of Fap1 substrates." (PMID 29899829, 2018). "Second, CD44v expression is inversely related to E-cadherin expression in colon cancer cells and CD44 overexpression in colon cancer cells enhanced EMT markers." (PMID 29652830, 2018). "A subsequent study has validated CD44 as a robust marker of highly tumorigenic colon cancer cells with stem-cell-like properties." (PMID 29652830, 2018). "Increased expression of CD44 known as hematopoietic cell E-/L-selectin ligand (HCELL) on colon carcinoma resulted in an enhanced adherence to activated endothelium." (PMID 28680883, 2017). "Using the stem cell markers CD133, CD166 and CD44, we found a subpopulation of highly tumorigenic human colon cancer cells." (PMID 29110645, 2017). "Our earlier work in breast and colon cancers found that knockdown of PIAS1 repressed CD44 expression." (PMID 29383121, 2017). "A correlation between YAP1 and Ascl2 was present not only in the CD133+CD44+ CRC cell population but also in colon cancer tissue samples." (PMID 29312609, 2017). "The levels of CD133, CD166 and CD44 in spheroid cells was remarkable higher than in primary colon cancer cells, suggesting that the three molecules are mainly existed in undifferentiated tumor cells." (PMID 29110645, 2017). "A recent research showed that CD44+CD166+ colon cancer cells have greater ability to form xenografts in nude mice than CD44+CD166−, CD44−CD166+ or CD44−CD166− cells." (PMID 29110645, 2017). "Previous studies in breast and colon cancer indicated that the effect of SUMO inhibition on CD44 expression was dependent upon TFAP2A." (PMID 29383121, 2017). "Together with the shorter survival of CSCs observed in long-term cultures and the reduction of β-Catenin expression and CD133+/CD44+ population, this result strongly supported Rimonabant ability to control colon cancer stem cells and their plasticity." (PMID 29354056, 2017). "The results are in agreement with experiments in colon cancer cell lines showing that the SUMO resistant mutant K10R repressed CD44 expression." (PMID 29383121, 2017). "The results indicated that the CD133+CD44+ CRC cell population represented colon cancer progenitor cells." (PMID 29312609, 2017). "Using three different gene datasets representative of differentiated Caco-2 cells, we found the remaining of well-described colon cancer phenotype markers CD44 and BMP4 in accordance with a poor healthy phenotype restoration." (PMID 28726765, 2017). "CD44 is one of the most frequently described markers of cancer initiating cells in numerous other malignancies and has been described as a signature of colon carcinoma initiating cells." (PMID 27764803, 2016). "While the N-glycans on CD44 facilitate HSPC binding to E-selectin, it is the CD44 O-glycans that facilitate E-selectin recognition in LS174T colon carcinoma cells." (PMID 27458028, 2016). "Analysis of CD44+CD24lo cells in human colon carcinoma cell lines indicated that six of eight human colon carcinoma cell lines contain a subset of CD44+CD24lo cells, and the majority of CD44+CD24lo cells are also CD133+CD24lo cells." (PMID 27659530, 2016).
colon carcinoma (continued). "The scope of CD133+CD44+CD24lo as human colon cancer stem cells and 5-FU resistance biomarker requires further studies since certain human colon carcinoma cells (i.e. LS411N) harbor 5-FU-resistant cell subsets but lack CD44+CD24lo cells." (PMID 27659530, 2016). "In contrast, more than 37% of cells are CD44+ in four of the seven human colon carcinoma cell lines." (PMID 27659530, 2016). "CD44 rs8193 is an independent prognostic marker for high-risk stage II and stage III colon cancer patients." (PMID 27323782, 2016). "Further, as CD24 as well as CD44-positive subpopulations from colon cancer cell-lines have been reported to possess stem cell-like properties, we examined effects on this population in SW480 and HT29 cells, using flow cytometry analysis." (PMID 27283988, 2016). "Higher levels of CD44 mRNA are mainly in brain, stomach, pancreas, liver, and colon cancer tissues, compared with their matched normal tissues." (PMID 27323782, 2016). "CD44 expression in the colon cancer tissue was substantially higher than that in normal mucosa and it correlates with cancer progression and aggressiveness." (PMID 27323782, 2016). "We sought to determine the relationship between CD133/CD44 expression and colon cancer cell sphere formation potential." (PMID 27659530, 2016). "We planned to use RNAi technology to down regulate CD133 and CD44 in colon cancer cells to see if it decease the tumorigenic capacity." (PMID 26840024, 2016). "On the other hand, HT-29 and T84 TS colon cancer cells are enriched in CD44+, CD133+ and/or CD326+ cells." (PMID 26752044, 2016). "In HT-29 colon cancer cells, the expression of CD44+/CD133+/CD326+ was significantly higher for TS1 and TS2 in comparison to TR1, although only TS2 showed a significant increase in the proportion of cells with this phenotype when compared to the TP." (PMID 26752044, 2016). "Three (MYC, CCND1 and CD44) of the six downstream targets were reported to be transcriptionally regulated by the Wnt signaling in the colon carcinoma cells from which the HCT 116 (the cell line we used in this study) was derived." (PMID 26057633, 2015). "Consistent with this, treatment of HT29 and CaCo2 colon cancer cell lines with NaBu also causes a reduction in the expression of CD133 and CD44." (PMID 26305601, 2015). "A study focused on colon cancer has also demonstrated that CD44 expressed on the cell surface can facilitate binding endothelial P- or L-selectin and increase haematogenous spread of tumor." (PMID 25823654, 2015). "The majority of colon cancer cells were positive for putative cancer stem cell markers, including CD44, CD133 and EpCAM, with the exception of KM12C cells, of which only ~55% were positive for CD133." (PMID 25789015, 2015). "We recently found variants in cancer stem cell genes (CD44, ALCAM and LGR5) significantly associated with increased time to recurrence (TTR) in patients with stage III and high-risk stage II colon cancer treated with 5-fluorouracil (5-FU)-based chemotherapy." (PMID 25665511, 2015). "Cancer-related gene c-MYC promoter was validated to combine with CD44 in colon cancer stem cells; SOX2 was chosen for its indispensable position in various CSCs." (PMID 26540347, 2015). "In the intestinal mucosa, CD44 is a major direct target of β-catenin mediated transcription, and we have shown that CD44v6 also regulates β-catenin in colon cancer cells." (PMID 25999946, 2015). "Knockdown of CD44 by lentiviral RNA interference in primary colon cancer cell lines reduced clonogenicity in vitro and tumourigenicity in vivo." (PMID 26569228, 2015). "Knockdown of CD44 decreased the adhesiveness of human colon cancer cells to HA, cancer colony-forming ability in soft agar assays, and xenograft tumorigenicity, while increasing susceptibility to etoposide-induced apoptosis." (PMID 26322272, 2015). "Knockdown of CD44 in primary colon cancer cell lines reduces clonogenicity in vitro and tumorigenicity in vivo." (PMID 24765173, 2014).
colon carcinoma (continued). "In this study we first demonstrate, in accordance with previous studies, that the three colon cancer cell-lines were CD44 positive (∼90%) with a broad intensity spectrum in the same cell line, from low to high CD44 expressing cells." (PMID 24760019, 2014). "DMP-1 is known to contribute to the invasion of colon cancer cells in a RGD-independent manner by bridging MMP-9 to CD44." (PMID 25396425, 2014). "EMT has also been shown to be involved in cancer stem-cells where colon cancer cells with a high expression of CD133/CD44 showed EMT after long-term culture." (PMID 24760019, 2014). "The ALDHBr/CD44+ population and ALDHBr/CD133+ population derived from human primary colon carcinoma exhibited higher tumor-initiating ability than that of ALDHBr, CD44+ and CD133+ populations." (PMID 23967051, 2013). "CD44 has also been identified as a marker of cancer stem cells in breast, head and neck, and colon cancer." (PMID 23426189, 2013). "Globally these findings seem to go along with our observation that low levels of CD44 are relevant for time to relapse in colon cancer." (PMID 24023782, 2013). "For example, treatment of HCT116 colon cancer cells with papain (enzyme used for dissociation of some solid tumors) reduced the detection of CD44 from 93.4% down to 0.5% of cells while EpCAM and CD133 (AC133) were not significantly affected." (PMID 23308131, 2013). "A recent study using short hairpin RNA against CD44 to silence its expression in SW620 colon cancer cells showed that reduced expression of the protein inhibited cell proliferation, migration, and invasion." (PMID 23527181, 2013). "CD44 in particular has been identified as a marker for stem cells in colon cancer, which is a high-morbidity tumor." (PMID 23800986, 2013). "In colon cancer cells, CD44 translocates into nucleus and directly interacts with STAT3 in response to osteopontin." (PMID 23326564, 2013). "CD44 is a cell surface receptor for hyaluronan, and a known metastasis suppressor in breast, prostate and colon cancer." (PMID 23857777, 2013). "We recently reported that CD44 is the major functional fibrin receptor on colon carcinoma cells, and that CD44-fibrin binding interaction is dependent on chondroitin and dermatan sulfate glycosaminoglycans." (PMID 23056168, 2012). "In summary, this study offers a novel perspective into the mechanism by which PGDF regulates CD44-dependent binding of metastatic colon carcinoma cells to fibrin(ogen) pertinent to the process of cancer metastasis." (PMID 23056168, 2012). "Collectively, these data offer a novel perspective into the mechanism by which PGDF regulates CD44-dependent binding of metastatic colon carcinoma cells to fibrin(ogen)." (PMID 23056168, 2012). "We have recently reported that CD44 is the major functional fibrin receptor on colon carcinoma cells." (PMID 23056168, 2012). "Blocking sulfation of CD44 from LS174T colon carcinoma cells resulted in a significant increase in LS174T CD44-coated microsphere binding to immobilized fibrin under flow." (PMID 23056168, 2012). "Although CD133, CD44, EpCAM were used extensively as cell surface markers for colon cancer stem cells, there were still doubts on these cell surface markers." (PMID 22745705, 2012). "The majority of the colon cancer cell lines (11/14) expressed CD44 on almost every cell (ranging 78.3% to 97.6%)." (PMID 22433494, 2012). "In colon cancer, for instance, it has been proposed that the CD44+/CD24−/CD133− profile represents the tumour stem cell population while CD133+ rather marks more differentiated cells." (PMID 22110593, 2011). "CD44 expression is up-regulated in several tumor types, such as breast cancer, gastric cancer, bladder cancer, head and neck cancer, colon cancer, hepatocellular carcinoma." (PMID 21819617, 2011).
colon carcinoma (continued). "CR colon cancer cells were also investigated for dual staining for surface markers that play significant role in adhesion, namely CD44 and CD166." (PMID 21774804, 2011). "In colon cancer, an overlap for EpCAMhi/CD44+ cells and a minor proportion of the CD133+ population has been found." (PMID 24212957, 2011). "CD44 is a widely used marker for TICs studies, especially in gastrointestinal tumors such as gastric and colon cancer." (PMID 21731740, 2011). "CD44+ populations have being found to be enriched in breast, prostate, head and neck, and colon tumors among others." (PMID 24212957, 2011). "CD44+CD166+ colon cancer cells display a higher ability to form tumors in immunodeficient mice as compared to CD44+CD166−, CD44−CD166− or CD44−CD166− cell populations, making this an useful combination for the identification of colon CSCs." (PMID 21311095, 2010). "For instance, knockdown of CD44 in primary colon cancer cell lines reduces clonogenicity in vitro and tumorgenicity in vivo." (PMID 21311095, 2010). "Endogenous miR-215 was elevated about 3-fold in CD133+HI/CD44+HI colon cancer stem cells that exhibit slow proliferating rate and chemoresistance compared to control bulk CD133+/CD44+ colon cancer cells." (PMID 20433742, 2010). "CD44 expressed on the surface of colon cancer cells has been shown to facilitate binding to endothelial P- or L-selectin and increase tumor access to haematogenous spread." (PMID 21124918, 2010). "Subsequently, Dalerba and Haraguchi reported that markers for colon cancer stem cells are EpCAM hi/CD44+/CD166+." (PMID 19583834, 2009). "CD133+ colon cancer cells include EpCAM hi/CD44+ cells, whereas the relationship between CD133+ subset and Lgr5+ subset is unclear." (PMID 19583834, 2009). "The expression of these ligands correlates with a high potential of bone metastasis: HCELL, which binds to L- and E-selectin, was found on LS174 colon carcinoma cells, as well as further variants of CD44 that allow L-, E- and P-selectin interactions." (PMID 19055814, 2008). "Similar up-regulation of tumor cell integrins and integrin-mediated adhesion by CD44 ligation was also found in a colon cancer cell line." (PMID 18350162, 2008). "We aimed at regulating the expression of CD44 in the highly metastatic human colon cancer cell line HM7 and thereby affecting its metastatic ability." (PMID 12439723, 2002). "A study detected three isoforms of circulatory CD44 (solCD44v8-10) in people with colon cancer." (PMID 41440277, 2025). "Moreover, another in vivo study has demonstrated the mechanisms of the SPP1 – CD44 axis in colon cancer in a mouse model, that the osteopontin acts as an immune checkpoint to suppress T cell activation and promotes tumor immune evasion in colon carcinoma." (PMID 39691723, 2024). "In colon cancer, GSCs are characterized by an increased ability of self-renewal, therapeutic resistance, and metastasis, and have been identified through surface markers such as CD44+, CD166+, ALDH+, CD44v6+." (PMID 38233377, 2024). "Accordingly, our study generated a unique panel of specific CD44 antibodies that react to different epitopes along the entire length of the CD44 molecule in order to comprehensively investigate the expression of different CD44 isoforms in normal colonic epithelium and in colon carcinomas." (PMID 37005380, 2023). "In addition, in this case the interaction between HA and CD44 R was exploited, demonstrating the ability of HA-based nanoparticles to selectively target murine colon carcinoma cells that were CD44 positive." (PMID 37373443, 2023). "We hypothesized that dual targeting of the CD44 and folate receptors on colon cancer cells would increase the targeting of nanoparticles, compared to single-targeted particles, and that it would be a function of surface ligand density." (PMID 37685852, 2023). "NAP, in addition to inhibiting STAT3, may also inhibit STAT1, thereby inhibiting the expression of CD44, and the stemness of colon cancer." (PMID 36732759, 2023).